MTOR (mechanistic target of rapamycin kinase)
Diseases named in the same sentence as MTOR in open-access papers (continued):
Sharing a sentence is not in itself a finding about the gene and the disease.
psoriasis (continued). "In the context of psoriasis, PI3K is observed to bind to Akt, leading to the subsequent activation of mTOR." (PMID 37935955, 2023). "Hyperactivated mTOR signaling, including phosphorylated- S6K-1, 4E-BP1 and AKT, are observed in lesional skin of psoriasis patients, supporting a pathological function of mTOR in psoriasis." (PMID 35938153, 2022). "Multiple signaling pathways (e.g., mTOR, JAK/STAT, and MAPK) are also involved in the pathogenesis and progression of psoriasis." (PMID 36618400, 2022). "The complex pathogenesis of psoriasis is regulated by the interplay between several signaling pathways, including JAK2/STAT3 and Akt/mTOR." (PMID 36501124, 2022). "Overall, the application of ADE relieves psoriasis-like skin inflammation possibly by regulating the Akt/mTOR and JAK2/STAT3 signaling pathways, making it an effective alternative for psoriasis therapy." (PMID 36501124, 2022). "Next we found that fisetin treatment resulted in inhibition of mTOR and induction of autophagy, leading to preclinical alleviation of IMQ-induced psoriasis-like skin inflammation, skin thickness and scaling." (PMID 36741386, 2022). "In psoriasis, the PI3 K/Akt signaling pathway is discovered to be over-activated that encourages the phosphorylation of mTOR and promotes the proliferation of keratinocytes in psoriasis lesions." (PMID 34355664, 2021). "Several signaling pathways including the nuclear factor κB (NF-κB), Mitogen-activated protein kinase (MAPK), mammalian target of rapamycin (mTOR), and tumor necrosis factor α (TNF-α) play crucial roles in the onset of psoriasis." (PMID 34113484, 2021). "In our exploration of the role of lncRNA H19 and miR-766-3p in psoriasis, we found that the AKT/mTOR pathway was activated by overexpression of miR-766-3p and that lncRNA H19 lessened the expression of the pathway." (PMID 34992498, 2021). "It is observed in psoriasis that PI3K binds to Akt and thereby in turn activites the mTOR to promote keratinocyte hyperproliferation and inhibite differentiation." (PMID 34067630, 2021). "The western blot results revealed that there were dramatic increases in the proportion of p-Akt/Akt, p-mTOR/mTOR, raptor, p-S6K1/S6K1 and p-S6/S6 in mice with IMQ-induced psoriasis." (PMID 34456715, 2021). "In our study, it was shown that GA inhibited the phosphorylation of mTOR and increased the CD4+FoxP3+ Treg frequency in spleen and lymphonodus in mice with imiquimod-induced psoriasis." (PMID 32908937, 2020). "In conclusion, GA ameliorated the symptoms of psoriasis, at least in part, through inhibition of inflammatory cytokines and STAT3/mTOR signaling and activation of Tregs in both lymph nodes and spleens." (PMID 32908937, 2020). "Collectively, our data identify the prodifferentiative, antiproliferative, and anti-inflammatory effects of fisetin, via modulation of the PI3K-Akt-mTOR and p38/JNK pathways and the production of cytokines in 2D and 3D human skin models of psoriasis." (PMID 31540162, 2019). "We modeled this aberrant mTOR activation using the synthetic mTOR agonist MHY 1485, which induced psoriasis-like skin changes especially skin thickening and delocalization of involucrin." (PMID 28700632, 2017). "To further verify that hyperactivation of mTORC1 is the reason for improper differentiation in psoriasis, we used the synthesized compound MHY1485 that was designed to specifically activate mTOR signaling." (PMID 28700632, 2017). "Collectively, these findings suggest that limonin plays a central role in inhibiting mTOR signaling through AMPK activation, regulating mitochondrial ROS production in IL-17-stimulated keratinocytes, and reducing the expression of psoriasis-related inflammatory factors." (PMID 39765869, 2024).
psoriasis (continued). "We investigated whether the anti-inflammatory effect of limonin regulates the expression of mTOR and its subcomplex, mTORC1, in TPA-induced psoriasis mice." (PMID 39765869, 2024). "Nevertheless, while mTOR fold increase did not correlate with FoxO1 in psoriasis patients, a significant correlation was found between mTOR and FoxO1 in AV patients." (PMID 38646331, 2024). "In addition, GA was reported to ameliorate psoriasis symptoms by inhibiting inflammatory cytokines and the STAT3/mTOR signaling pathway." (PMID 37643205, 2023). "Upon activation of the mTOR network, diverse cytokines and other pro-inflammatory mediators, such as IL-6, CXCL8, and IL-22, are released, which increases the inflammation and proliferation of cells commonly seen in psoriasis." (PMID 37371141, 2023). "Through our findings, we speculated that the decreased AKT/mTOR/HIF-1α signaling and glycolytic ability in γδ T cells may contribute to the suppression of psoriasis achieved by D-mannose." (PMID 35296088, 2022). "Akt has been shown to be highly activated in skin of psoriatic lesions, except in the basal layer and mTOR, expression is found to be increased in lesional and Non-lesional skin of psoriasis patients." (PMID 35265634, 2022). "Most importantly, we determined that D-mannose, a hexose sugar, could alleviate the experimental psoriasis by suppressing γδ T cells via inhibition of glycolysis and AKT/mTOR/HIF-1α signaling." (PMID 35296088, 2022). "However, the effects and detailed molecular mechanisms of the mTOR inhibitor rapamycin and TCDD on psoriasis in vivo remain to be elucidated." (PMID 33921372, 2021). "PI3K-Akt signaling, a crucial pathway responsible for regulating survival signals, was reported to be hyper-activated in the keratinocytes in psoriasis lesions, which subsequently phosphorylated the downstream target proteins FOXO and mTOR, thereby promoting keratinocytes proliferation." (PMID 32493482, 2020). "Furthermore, these findings suggest that fisetin exerts inhibitory functions on the two major cell types involved in psoriasis pathogenesis, keratinocytes, and immune cells by inhibiting the activation of PI3K/AKT/mTOR and MAPK pathway components." (PMID 31540162, 2019). "Besides, rapamycin, an inhibitor of mTOR, could exert antiproliferative properties in the imiquimod (IMQ)-induced mice psoriasis via activating NRF2 signaling and restraining NOX2/4 from decreasing ROS generation." (PMID 36242051, 2022). "Concomitantly, mTOR signaling pathway in turn enhances keratinocytes to produce proinflammatory molecules, including IL-6, CXCL8 and VEGF in response to TNF-α, suggesting that a feedback loop driven by mTOR signaling triggers and aggravates the pathogenesis of psoriasis." (PMID 35938153, 2022). "The novel mTOR inhibitors may be simultaneously beneficial for several psoriasis-related inflammatory and noninflammatory comorbidities." (PMID 33921372, 2021). "In addition, not only the clinical symptoms of psoriasis, such as erythema, thickening, and scaling, but also the skin inflammation cytokines are alleviated through the downregulation of p-phosphoinositide 3-kinase (PI3K) and p-mTOR by treatment with MC-EO in a mouse model of IMQ-induced psoriasis." (PMID 38791435, 2024). "We assume that mTOR hyperactivation might have a dual effect on the processes leading to the psoriatic phenotype: In cells that still have the capacity to divide, mTORC1 signaling enforces proliferation contributing to the acanthosis seen in MHY1485 mice and in psoriasis." (PMID 28700632, 2017). "HIF-1α and its regulators (HDAC-1, HDAC-7, VHL-E3, PHD2, LL-37, HIF-1β, mTOR, miR-210, RORγt, STAT3, and IL-13Ralpha, as well as glycolysis enzymes) could be important pharmacological targets to restore the lack of regulation in the angiogenesis and in immunological processes involved in psoriasis." (PMID 26136626, 2015).
psoriasis (continued). "Various studies indicate that the mTOR and STAT3 pathways are significant for psoriasis development; however, in mouse models, mTORC2, not STAT3, deletion results in a mitigated psoriasis profile and changes in the γδ17 T cells profile." (PMID 40276509, 2025). "Components of the PI3K/Akt/mTOR pathway and its downstream effector molecules (e.g., S6K1) have been reported to be hyperactivated in stained psoriasis patient skin lesions compared to healthy control or non-lesional skin." (PMID 37371141, 2023). "Fourthly, the signaling molecules involved in HFD- or propionate-induced attenuation of psoriasis-like dermatitis have not been clarified and should comprehensively be analyzed, such as NF-κB, STAT3, mTOR, or TLR7." (PMID 37762500, 2023). "Our study has shown that (i) no serious risks for health exist for psoriasis patients willing to fast, (ii) fasting has a beneficial effect in terms of PASI score reduction, and (iii) this effect was particularly evident in patients treated with apremilast or mTOR inhibitors." (PMID 30691245, 2019).
renal fibrosis (92 papers, 2012 to 2026). A final common manifestation of a wide variety of chronic kidney diseases characterized by glomerulosclerosis and tubulointerstitial fibrosis. "In LN, the abnormal activation of the PI3K-AKT pathway and its downstream mTOR signaling pathway is directly linked to inflammation, immune dysregulation, and renal fibrosis." (PMID 40573311, 2025). "Application of insulin-like growth factor 1 receptor (IGF-1R) inhibitor further confirmed that the regulation of autophagy and renal fibrosis by HDHW was associated with IGF-1-mediated activation of the PI3K/Akt/mTOR pathway." (PMID 36160409, 2022). "Heterozygosity for AP-2β in nephron progenitor cells leads to progressive distal convoluted tubule abnormalities and β-catenin/mTOR hyperactivation that is associated with renal fibrosis and cysts." (PMID 35468900, 2022). "Numerous pathways, such as TGF-β1/Smads, PDGF, Wnt/β-catenin, and mTOR signalings, have been implicated in renal fibrosis." (PMID 33634104, 2020). "The results indicated that the expression of urinary mTOR decreased every one unit; the risk for renal fibrosis elevated 10.358 times." (PMID 31485275, 2019). "Thirdly, to confirm the diagnostic value of urine mTOR mRNA in renal fibrosis and even the mesangial hypercellularity and endocapillary cellularity, a larger group of validation study and a long-term follow-up study are also necessary." (PMID 31485275, 2019). "Activation of the mTOR pathway has been associated with extracellular matrix synthesis and renal fibrosis." (PMID 25285155, 2014). "For example, AGEs can upregulate RAGE expression, activate multiple signaling pathways, including JAK-STAT, MAPK/ERK, PI3K/Akt/mTOR, and NF-κB, and increase oxidative stress, inflammation, and renal fibrosis, causing structural and functional disorders in the kidney of patients with DM." (PMID 34539795, 2021). "Also, many animal experiments have proved that inhibition of mTOR signaling can markedly ameliorate renal interstitial inflammation, renal dysfunction and renal fibrosis associated with CKD." (PMID 32372953, 2020). "Further, we evaluated the diagnostic value of urinary mTOR mRNA expression for renal fibrosis." (PMID 31485275, 2019). "A better understanding of the underlying mechanisms of mTOR signaling in renal fibrosis might help to find out a way to halt the fibrotic progression." (PMID 22470459, 2012). "A study by Ren et al94 found that macrophage activation is closely linked to the mTOR pathway, and targeting this pathway in macrophages can alleviate renal fibrosis, suggesting it could be a potential avenue for preventing the progression of renal fibrosis in DN." (PMID 39717716, 2025). "Thus, we hypothesized that renal fibrosis in kidneys of Six2Cre+Tfap2bfl/fl mice would be associated with increased β-catenin/mTOR activity." (PMID 35468900, 2022). "Mechanistically, GDF15 ameliorates renal fibrosis by enhancing autophagy through the PI3K/Akt/mTOR pathway." (PMID 41474228, 2026). "TCM has been shown to inhibit the mTOR pathway, promote autophagy, protect renal function, and reduce renal fibrosis." (PMID 40337513, 2025). "Our study further confirmed this effect of zinc supplementation in inhibiting the EMT process with another mechanism that renal fibrosis was attenuated by suppressing the activity of the TGF-β1/PI3K/AKT/mTOR pathway." (PMID 39028478, 2025). "Activation of mTOR is observed in various types of kidney diseases, and multiple studies have elucidated its involvement in renal fibrosis development." (PMID 39028478, 2025). "For example, fucoidan, a natural marine polysaccharide, can inhibit podocyte pyrogenesis and reduce renal fibrosis in DN by regulating the AMPK/mTOR/NLRP3 signal axis." (PMID 39717716, 2025). "For instance, TMAO triggers NLRP3 inflammasome formation and activates NF-κB signaling, Caspase-1, the PERK/Akt/mTOR pathway, and IL-1β, leading to increased renal fibrosis." (PMID 40134790, 2025).
renal fibrosis (continued). "The first is the nuclear enriched abundant transcript 1 (NEAT1) that regulated Akt/mTOR signaling, which is a pathway associated with EMT in renal fibrosis progression." (PMID 41233312, 2025). "While TGF-β/Smad and Wnt/β-catenin represent the most extensively characterized pathways in renal fibrosis, recent studies highlight the roles of mechanistic target of rapamycin (mTOR) and peroxisome proliferator-activated receptor gamma (PPARγ)." (PMID 40141260, 2025). "Emodin, a natural compound, can inhibit apoptosis, enhance podocyte autophagy, and alleviate renal fibrosis in DN rats by modulating the renal AMPK/mTOR signaling pathway." (PMID 39717716, 2025). "By inhibiting ECM production, myofibroblast proliferation and migration, and key signaling pathways such as TGFβ and mTOR, pirfenidone holds potential as a therapeutic strategy to mitigate renal fibrosis in ADPKD." (PMID 40909512, 2025). "In animal studies on hyperuricemic nephropathy, TMAO accelerates renal fibrosis by activating PI3K/AKT/mTOR pathway." (PMID 40134790, 2025). "Chlorogenic acid (from Lonicera japonica) was observed to inhibit TMAO-synthesizing bacteria (Faecalibaculum and Blautia) and activate the PI3K/AKT/mTOR pathway, reducing renal fibrosis and oxidative stress." (PMID 40895468, 2025). "In summary, exosomes can affect the level of autophagy by targeting downstream autophagy‐related regulatory pathways, such as mTOR or ATGs, thereby promoting or inhibiting renal fibrosis." (PMID 38898750, 2024). "Tretinoin downregulates miR-141-3p in human mesangial cells (HMC) induced by HG, activates PTEN/Akt/mTOR pathway, restores autophagy, and reduces renal fibrosis." (PMID 39707216, 2024). "Taken together, our data demonstrate that ASIV ameliorates renal fibrosis by promoting the expression of ALDH2 to regulate AKT/mTOR-mediated autophagy." (PMID 37443810, 2023). "In pulmonary and renal fibrosis, mTOR signaling pathways are upregulated in disease-related fibroblasts and promote collagen synthesis." (PMID 37159282, 2023). "Emodin has been found to reduce renal fibrosis in DN rats by regulating the AMPK/mTOR signaling pathway in the kidney, promoting podocyte autophagy, and inhibiting apoptosis." (PMID 35978370, 2022). "Taken together, these data suggest that the suppression of mTOR by ODN can modulate autophagy in UUO-induced renal fibrosis." (PMID 36232665, 2022). "Toward these ends, it investigates the inhibitory effects of mTOR/STAT3 decoy ODN on preventing renal fibrosis." (PMID 35164031, 2022). "To verify the ability of MK-2206 to attenuate renal fibrosis and its specific mechanism of action, we examined the phosphorylation levels of related proteins in the Akt-mTOR pathway." (PMID 36359901, 2022). "Rapamycin, which is an mTOR inhibitor, has shown that it can attenuate inflammation and renal fibrosis in various types of kidney disease." (PMID 36232665, 2022). "This study evaluated how the change in autophagy appearance by the inhibition of mTOR/STAT3 function affects renal fibrosis after injury." (PMID 35164031, 2022). "To further explore the specific mechanism of MK-2206 in alleviating renal fibrosis, we examined the phosphorylation levels of Akt/mTOR pathway-related proteins in vivo and vitro." (PMID 36359901, 2022). "In conclusion, our study showed that HDHW inhibited autophagy by upregulating IGF-1 expression, promoting the binding of IGF-1 to IGF-1R, and activating the PI3K/Akt/mTOR signaling pathway, thereby reducing renal fibrosis and protecting renal function." (PMID 36160409, 2022). "We have shown that dysregulation of the PI3K/AKT/mTOR signaling pathway mediates impaired autophagy in a diabetic model of renal fibrosis." (PMID 35015734, 2022). "Notch1 activation of the AKT/mTOR pathway subsequently suppressed autophagy, leading to the occurrence and development of renal fibrosis." (PMID 36348805, 2022).